ADAM20 (ADAM metallopeptidase domain 20)
Description:
May be involved in sperm maturation and/or fertilization.
Tractability: Antibody: its Gene Ontology location is reachable by antibodies, with high confidence; UniProt predicts a signal peptide or a membrane-spanning region. PROTAC: ubiquitination databases record sites on it.
Gene: Protein-coding gene on chromosome 14 (70,522,358 to 70,535,015, reverse strand). Ensembl gene ENSG00000134007.
Subcellular location: Membrane
Pathways (Reactome):
Reproduction: Interaction With Cumulus Cells And The Zona Pellucida
Gene Ontology:
Molecular function: metalloendopeptidase activity; metallopeptidase activity
Biological process: male gonad development; proteolysis; single fertilization
Cellular component: external side of plasma membrane; plasma membrane; sperm head plasma membrane; membrane
Genetic constraint (gnomAD): Loss-of-function variants: 1 observed, 0.4 expected, observed/expected ratio (o/e) 2.48. That is too few expected variants to judge how well the gene tolerates losing a copy. Missense variants: 871 observed, 932.63 expected, observed/expected ratio (o/e) 0.93, 90% interval 0.88 to 0.99. Synonymous variants: 305 observed, 330.12 expected, observed/expected ratio (o/e) 0.92, 90% interval 0.84 to 1.02.
Homologues: Orthologues: chimpanzee ADAM20 (99% identical), macaque ADAM20 (93% identical), pig ADAM20 (70% identical), dog ADAM20 (69% identical), mouse Adam39 (48% identical), mouse Adam25 (48% identical), rat Adam25 (48% identical), mouse Adam20 (47% identical), zebrafish adam9b (31% identical), Caenorhabditis elegans unc-71 (25% identical), zebrafish adam10a (20% identical), Drosophila melanogaster mmd (20% identical), and 1 more. Paralogues in human: ADAM21 (60% identical), ADAM29 (51% identical), ADAM30 (37% identical), ADAM9 (36% identical), ADAM19 (31% identical), ADAM12 (30% identical), ADAM33 (29% identical), ADAM8 (28% identical), ADAM22 (28% identical), ADAM32 (28% identical), ADAM15 (27% identical), ADAM2 (27% identical), and 8 more.
Diseases named in the same sentence as ADAM20 in open-access papers:
ADAM20 is named in the same sentence as 8 diseases in open-access papers, as found by Europe PMC text mining. Sharing a sentence is not in itself a finding about the gene and the disease. The quoted sentences say what the papers report.
COVID-19 (1 paper, 2022). A disease caused by infection with severe acute respiratory syndrome coronavirus 2. "We found that the expression of the antiviral genes negatively correlated (except ADAM7, ADAM11, ADAM12, ADAM18, ADAM20, and ADAM29) with the HRCT score of the COVID-19 patients suggesting association of increased antiviral response with decreased disease severity." (PMID 36532041, 2022).
gastric cancer (1 paper, 2013). A primary or metastatic malignant neoplasm involving the stomach. "In gastric cancer the expression of ADAM10, ADAM15, ADAM17 and ADAM 20 transcripts is markedly increased." (PMID 25437333, 2013).
male infertility (1 paper, 2024). The inability of the male to effect fertilization of an ovum after a specified period of unprotected intercourse. "The ADAM metallopeptidase domain 20 (ADAM20) gene is specifically expressed in testis and has been associated with male infertility in humans and mice." (PMID 39118059, 2024).
melanoma (1 paper, 2022). A malignant, usually aggressive tumor composed of atypical, neoplastic melanocytes. "With respect to the relationship between the level of baseline sPD-L1 and transcripts encoding 60 metalloproteases, ADAM11, ADAM20 and ADAMTS14 were identified as associated with higher baseline sPD-L1 levels in both CheckMate 009/RCC and CheckMate 038-P1/melanoma (t-values >1.5)." (PMID 35131863, 2022).
cardiovascular disease (1 paper, 2022). "So far, ADAM20 was found to have a role in managing cell fusion during reproduction but a possible relationship with cardiovascular disease is not defined." (PMID 35805966, 2022).
ADAM20 also shares sentences with these, for which no sentence is quoted: astrocytic tumor (1 paper); brain tumor (1); infertile (1).